EZH2 (enhancer of zeste 2 polycomb repressive complex 2 subunit)
Diseases named in the same sentence as EZH2 in open-access papers (continued):
Sharing a sentence is not in itself a finding about the gene and the disease.
tumor (continued). "The therapeutic potential of EZH2 pathway inhibition together with its associated mechanisms shows promise as a method to restore tumor‐suppressor genes and fight cancer development." (PMID 40959208, 2025). "EZH2, a histone methyltransferase involved in chromatin modification and gene transcription, is associated with higher tumor malignancy, differentiation, and metastasis in CC." (PMID 40352921, 2025). "Previous studies have shown that BPA alters chromatin states by upregulating epigenetic regulators such as EZH2, thereby increasing tumor susceptibility, which is consistent with these findings." (PMID 41465929, 2025). "High-risk HPV involvement in aberrant EZH2 expression of EZH2 is linked by correlation of p16, a tumour suppressor used as a potential marker for HPV infection with an elevated H3K27me3 epigenome in patients with HPV." (PMID 41614754, 2025). "EZH2 has been implicated in the pathogenesis and progression of several cancers, where its overexpression often correlates with aggressive tumour behaviour and poorer prognosis, in agreement with the current study." (PMID 40310411, 2025). "EZH2 overexpression in HB is associated with increased tumor cell proliferation, invasion, and metastasis." (PMID 40766612, 2025). "EZH2, a conserved histone lysine methyltransferase, is frequently overexpressed or mutated in a wide range of cancers, where it promotes tumor initiation, progression, and poor clinical outcomes." (PMID 40314246, 2025). "The machine learning approaches employed in this study provided a robust framework for identifying key molecular players in HCC, laying the groundwork for future studies aimed at to elucidating the underlying mechanisms of EZH2 in tumor progression." (PMID 41298718, 2025). "Application of the EZH2 catalytic inhibitor EPZ0011989 by oral gavage caused a reduction of tumour progression and increase immune infiltration." (PMID 38630912, 2024). "Overall, these analyses demonstrate that our tumor samples exhibit transcriptomic disparities as a function of EZH2 mutation status that are consistent with established observations." (PMID 38658543, 2024). "Our data suggest that when an LKB1-deficient tumor is squamous in epigenetic state, that EZH2 inhibition combined with immunotherapy will be an effective treatment approach." (PMID 38265267, 2024). "The association between PVRL3 and EZH2 suggests a complex network of interactions influencing tumor growth and immune evasion, offering new insights into the molecular mechanisms underlying TNBC and suggesting novel potential avenues for intervention." (PMID 39120328, 2024). "A confounding factor, however, is that the expression of EZH2 occurs in both tumor cells and in tumor-associated innate and adaptive immune cells (e.g., tumor-infiltrating neutrophils (TINs) and lymphocytes (TILs), respectively)." (PMID 38791429, 2024). "The H3K27M mutation seems to oppose the function of EZH2, which would otherwise act as a tumor suppressor." (PMID 39202398, 2024). "The data indicated that a higher EZH2-score was linked to a more undifferentiated tumor grading, a higher AJCC-stage, and an advanced pN-stage." (PMID 40135141, 2024). "The authors of the study showed that EZH2 was able to monomethylate RORa, causing a degradation of the protein through the ubiquitin–proteasome pathway, thereby inhibiting its tumor suppressive role." (PMID 39769907, 2024). "Our data showed that a higher EZH2 score was associated with a more undifferentiated tumor grading (score I, II, III), higher AJCC-Stage (score III) and advanced pN-stage (score II, III)." (PMID 40135141, 2024). "Compared to normal mucosa or adjacent normal tissues, 50–60% of HNSCC tissues exhibit overexpression of EZH2, which is closely associated with tumor differentiation status." (PMID 38600608, 2024).
tumor (continued). "Our findings indicate that a major mechanism underlying the anti-tumor effects of EZH2i in ATRTs is the induction of viral mimicry response, which holds potential implications for the clinical activity of targeting EZH2 in ATRT patients." (PMID 39472584, 2024). "Tumor cells with loss of SMARCB1 demonstrate a constitutive EZH2 activation and oncogenic activation." (PMID 38491228, 2024). "EZH2 is mutated repeatedly in a variety of cancers and plays an important role in tumor proliferation and progression." (PMID 38764053, 2024). "In the context of tumors, EZH2 is often overexpressed and associated with aggressive cancer phenotypes, metastasis, and poor prognosis, where it promotes tumor growth by silencing tumor suppressor genes and dysregulating various signaling pathways." (PMID 38534385, 2024). "Detecting urinary tumor-secreted cf-EZH2 serves as a diagnostic marker for predicting BCa patients' prognosis and distinguishes MIBC from NMIBC 75-78." (PMID 39113711, 2024). "The increased expression of EZH2 occurs in both tumor and TME-associated cells, such as T-cells, NK cells, regulatory T-cells and macrophages." (PMID 38254784, 2024). "Studies have also demonstrated that upregulation of EZH2 is linked to tumor invasiveness and poor prognosis in HNSCC." (PMID 38600608, 2024). "EZH2 knockdown in SMARCB1 deficient ecMRT tumors decreased the tumor growth rate, while targeting EZH2 with Ribavirin101 or DZNep102 led to increased survival in orthotopic AT/RT xenograft models." (PMID 39465218, 2024). "Evidence shows that mutation or overexpression of EZH2 is an important factor leading to tumor growth and migration." (PMID 38764053, 2024). "Enhancer of zeste homolog 2 (EZH2) is a transcriptional enzyme implicated in tumor development and is often correlated to poor patient outcomes in various malignancies." (PMID 40135141, 2024). "Our study confirms that EZH2 protein levels are associated with aggressive tumor behavior and poor outcomes in OS patients." (PMID 38886296, 2024). "The authors revealed that abnormal EZH2 expression was more often associated with ureteral location, sessile architecture, tumor necrosis and concomitant CIS." (PMID 39272712, 2024). "The inhibition of EZH2 was associated with the decreased proliferation and migration of mesothelial cells in vitro, as well as decreased tumor volume in MPM xenografts in vivo." (PMID 38610930, 2024). "We found a significant positive correlation between EZH2 expression and Ki-67 staining (r = 0.5467, p < 0.05), suggesting that EZH2 upregulation in ATLL is associated with an enhanced tumor proliferation index." (PMID 38339397, 2024). "EZH2 overexpression is associated with rapid tumor progression and EZH2 plays a critical role in the immune system." (PMID 38347129, 2024). "Next-generation sequencing, where 730 gene mutations such as KRAS, BRAF, and PIK3CA were detected by second-generation sequencing method based on target region capture, revealed an EZH2 gene mutation in the tumor cells." (PMID 38773600, 2024). "We previously investigated these potential regulators of EZH2 expression in various types of hematologic malignancies and found differential signaling cascades associated with different tumor types." (PMID 38339397, 2024). "This dynamic process underlines the role of HIF-1α in regulating EZH2-mediated epigenetic modifications that contribute to tumor cell dissemination and metastasis." (PMID 38911968, 2024). "Since EZH2 can be expressed in both TINs and TILs, further understanding its role and impact as a tumor-intrinsic and/or immune-associated factor is critical to overcoming TNBC resistance and improving patient outcomes." (PMID 38791429, 2024). "We further evaluated progression-free survival rates, and found that factors like tumor differentiation, lymph node metastasis, muscle invasion, tumor size, and EZH2 levels were risk factors for progression-free survival rates." (PMID 38476362, 2024).
tumor (continued). "The patient underwent surgery, and the incised tissues were subjected to pathology examinations, along with immunohistochemistry and next-generation sequencing tests suggestive of an EZH2 gene mutation in the tumor cells." (PMID 38773600, 2024). "EZH2 mutations found in diffuse large B-cell lymphoma increased the conversion of H3K27me1 to H3K27me2/3, ultimately activating a pro-tumor transcriptional program." (PMID 38473997, 2024). "Targeting EZH2 in cancers with activating EZH2 mutations or overexpression of EZH2 diminishes tumor growth, shown in preclinical studies." (PMID 39472584, 2024). "In the same cohort, univariate analysis revealed high EZH2 expression to be associated with poorer overall survival (OS) rates including all tumor entities (EZH2low vs. EZH2high: median OS 2.45 vs. 1.42 years; p = 0.0096)." (PMID 37297005, 2023). "EZH2 is an H3K27 methyltransferase associated with tumour angiogenesis that has become a significant hallmark of multiple cancers." (PMID 36619221, 2023). "EZH2 overexpression has been found in a variety of cancers including breast, prostate, endometrial, and melanomas, and is associated with increased tumour aggressiveness." (PMID 38275587, 2023). "Overexpression of EZH2 has been linked to tumor cell aggressiveness and poor prognosis in multiple myeloma." (PMID 38028538, 2023). "Mice with one floxed allele of Ezh2 (Ezh2 heterozygous; ∆/+) had significantly lower tumor burden when compared with Ezh2 wild-type (WT) mice." (PMID 36670102, 2023). "EZH2 inhibits genes involved in tumor suppression, and overexpression or mutation of the EZH2 gene has been linked to cancer." (PMID 37468555, 2023). "Other mechanisms by which EZH2 acts is by causing hypermethylation of CpG islands in promoter region of tumor suppressor gene miR-484 by recruiting DNA methyltransferase enzymes." (PMID 37131568, 2023). "In this study, U2AF1, DNMT3A, SF3B1, and EZH2 in the secondary tumor group was higher than that in the tumor‐free group, while the mutation rate of ASXL1, TET2, and KMT2D was higher in the tumor‐free group." (PMID 36727544, 2023). "Overexpression of EZH2 has been identified in a variety of neoplasms, which often accelerates tumor progression and associates with poor clinical outcomes." (PMID 38031139, 2023). "Mutations in EZH2, such as Y641 and A677/A687 mutations, enhance its enzymatic activity and promote tumor growth." (PMID 37752998, 2023). "The miR-124-3p quantity in PCa tumor tissues was inversely linked to EZH2, demonstrating that EZH2 directly affects miR-124-3p." (PMID 36884182, 2023). "ASXL1 mutations are frequent, with the disease displaying a higher prevalence of ETNK1, SETBP1, and EZH2 mutations in comparison to other MDS/MPN overlap neoplasms." (PMID 37370785, 2023). "Immunohistochemistry analysis of the tumors revealed reduced tumor cell proliferation and less recruitment of cancer-associated fibroblasts in the EZH2-edited tumors compared to the control tumors." (PMID 37175580, 2023). "Prognostic significance of EZH2 expression status has been also reported in patients with these tumours, because high expression of EZH2 was associated with tumor aggressiveness." (PMID 38146588, 2023). "The resulting dysregulation driven by EZH2 mutations has shown contrasting impacts in clinical cohorts, acting either as an oncogene or tumor suppressor." (PMID 37511137, 2023). "Accordingly, to explore the latent biological causal link between EZH2 and the interplay between tumor and immunity in LUAD, it is necessary to carry out additional in vivo or in vitro experiments." (PMID 37069494, 2023). "PRC2 shows both oncogenic and tumour‐suppressive roles; when EZH2 undergoes somatic mutations, its catalytic activity is hyperactivated rendering PRC2 to reveal its oncogenic side." (PMID 37277696, 2023). "Analysis showed that Ezh2 heterozygous tumors had significantly more tumor-associated lymphocytes/monocytes when compared with Ezh2 null tumors." (PMID 36670102, 2023).
tumor (continued). "So far, inhibitors of EZH2 seem to have the greatest potential of being used in adjuvant therapy, as EZH2 has been associated with tumor growth, metastasis and angiogenesis in several studies both in vivo and in vitro." (PMID 37228649, 2023). "In models of MPM overexpressing EZH2 due to BRCA-1-associated protein 1 (BAP1) loss, pharmacological EZH2 inhibition showed significant anti-tumor activity." (PMID 36900330, 2023). "EZH2 immunoexpression demonstrated significant association with histological subtypes of the tumor (p = 0.018)." (PMID 37131568, 2023). "In contrast, mice with two floxed alleles of Ezh2 (Ezh2 null, ∆/∆) had significantly higher tumor burden, significantly shorter survival, and significantly higher nuclear grades when compared to mice with Ezh2 WT or heterozygous tumors." (PMID 36670102, 2023). "Epigenetic circuitry containing EZH2 can promote hepatocarcinogenesis and is associated with tumor recurrence and poor survival in HCC." (PMID 38008711, 2023). "For instance, in tumor cells, the overexpression of the enhancer of zeste homolog-2 (EZH2), which is associated with the polycomb-2 repressor complex (PRC2), promotes cell proliferation, cell migration, and invasiveness under the influence of bFGF." (PMID 37048074, 2023). "In recent years, the relationship between EZH2 single-nucleotide polymorphisms (SNPs) and tumor genetic susceptibility has attracted the attention of many scholars." (PMID 36672374, 2023). "Mutations in MLL2 (KMT2D) and TET2 were associated with inferior prognosis in ENKTL, and overexpression of EZH2 was associated with higher tumor cell proliferation, advanced stage, and inferior survival." (PMID 36900160, 2023). "EZH2 is overexpressed or mutated in a wide spectrum of cancers and associates with tumor initiation and progression as well as poor clinical prognosis and outcomes." (PMID 37069142, 2023). "Sequencing studies have identified both loss of function and gain of function mutations of EZH2 in various hematologic malignancies suggesting that it acts as both a tumor suppressor and an oncogene." (PMID 38028538, 2023). "High levels of EZH2 in tissue from HCC patients are associated with tumor aggressiveness and poor prognosis, and previous studies suggested that EZH2 accumulation is a potential cause of acquired resistance to chemotherapy and immunotherapy." (PMID 37085881, 2023). "High immunoexpreesion of EZH2 exhibited a significant association (p < 0.05) with the tumor grade, histologic subtype, lymphnode metastasis, and FIGO stage." (PMID 37131568, 2023). "Enhanced antigen presentation on the tumor cells by EZH2 inhibitors or CRISPR-mediated EZH2 deficiency have been shown to increase antigen-specific CD8+ T-cell proliferation, IFN-γ production, and tumor cell cytotoxicity." (PMID 36627707, 2023). "In MM, EZH2 overexpression is involved in biological processes including proliferation, apoptosis and side-population maintenance of tumor cells, and is also associated with cellular drug resistance." (PMID 37239949, 2023). "The study findings illuminated a compelling association between EZH2 expression in tumor cells and patient prognosis." (PMID 37909018, 2023). "In contrast, EZH2 depletion caused an miR-124-3p-dependent inhibition of CCL2 expression in the tumor cells, leading to the inhibition of M2 polarized activation." (PMID 36900330, 2023). "To further investigate the mechanism underlying the antitumor effect, we analyzed xenograft tumor sections using immunohistochemistry to verify EZH2 and LC3 expression." (PMID 35402377, 2022). "As a key epigenetic regulator, besides its role in controlling the proliferation of tumor cells, EZH2 has been implicated in the regulation of various immune cells including macrophages." (PMID 35432300, 2022). "All cases had tumor and peripheral blood samples and were analyzed for mutations at codon 641 in exon 16 of EZH2." (PMID 36230571, 2022).
tumor (continued). "Patients who were offered combined adjuvant chemo- and radiotherapy were also those diagnosed with at least a grade 3 tumour, and hence, were significantly associated with higher EZH2 protein expression (p = 0.003)." (PMID 36292072, 2022). "LATS2, functioning as a tumour suppressor gene regulated by EZH2, was mutated in NSCLC, and overexpression of LATS2 induced cell apoptosis and inhibited NSCLC cell growth." (PMID 35379783, 2022). "Mechanistically, the KRAS status determines the transcriptional consequences of EZH2-dependent targeting of the NFATc1 gene, encoding for an inflammatory tumor-progressive transcription factor." (PMID 35884510, 2022). "Multiple logistic regression analysis showed that high expression of RUNX3 and low expression of EZH2 were significantly associated with good tumor regression (TRG grade 0/1) (P = 0.021, P = 0.016) and tumor down-staging (P = 0.014, P = 0.043)." (PMID 35280723, 2022). "Loss of EZH2 dramatically reduced CCL2 expression in the tumor cells, while EZH2 inhibitor conducted an opposite effect." (PMID 36038549, 2022). "Recently, researchers have found EZH2 inhibitor is able to weaken drug resistance caused by metabolic activities in tumor." (PMID 35935878, 2022). "Overexpression of EZH2 is strongly associated with advanced stages of cancer progression, and tumor metastasis by regulating EMT pathway in a variety of cancers." (PMID 36316365, 2022). "On the other hand, although the SMARCA4 loss is not directly targetable, Januario and collaborators demonstrated that inhibiting histone methyltransferase EZH2 was effective in SMARCA4-mutated cancer cell lines derived from various tumor types." (PMID 35884575, 2022). "In tumor cells, EZH2 mutations down-regulate the expression of tumor antigens, thereby evading specific immune recognition by T cells." (PMID 36713412, 2022). "Knockout of SMARCB1 in mice causes tumor formation with 100% penetrance, and these tumors were highly dependent on EZH2." (PMID 35169119, 2022). "The methylation levels of H3K9 modulated by G9a and H3K27 modulated by EZH2 are often increased in cancer and associated with tumor progression." (PMID 35409271, 2022). "Both the high expression of EZH2 and the low expression of the p57 gene promoted the occurrence of small hepatocellular carcinoma, and the deficiency of the p57 gene in tumor foci was related to the low differentiation of cancer cells." (PMID 35321452, 2022). "The high EZH2 expression group was significantly associated with older age group (p = 0.003), higher tumour grade (p < 0.001), and IDH1 R132H immunonegativity (p = 0.039)." (PMID 36292072, 2022). "Collectively, we suggested that tumor angiogenesis should be evaluated as an additional mechanism underlying the pro-metastatic activity of TAMs in mice treated with EZH2 inhibitors." (PMID 36038549, 2022). "Diagnostic ROC curve analysis demonstrated that EZH2 expression can effectively distinguish tumor and normal tissue (AUC = 0.897)." (PMID 36358967, 2022). "In most cancer entities (e.g., pancreatic cancer, breast cancer, prostate cancer, lung cancer), EZH2 is clearly associated with pro-tumorigenic and tumor-progressive characteristics." (PMID 35740494, 2022). "Currently, it has been reported that the pro-tumor activity of PRC2 is mainly associated with its EZH2, EED, and SUZ12 subunits." (PMID 36076977, 2022). "Together, EPZ6438 and MAK683 are potent PRC2 inhibitors, and they inhibit proliferation of tumor cells with EZH2-GoF mutation or deficiency of SWI/SNF complex." (PMID 35169119, 2022). "In total 6 EZH2 variants were identified in four FL patients, of which two were present in both cfDNA and tumor tissue DNA." (PMID 35795062, 2022). "It has been demonstrated that EZH2 is overexpressed in a variety of malignancies and is associated with a poor prognosis and that downregulating EZH2 expression can inhibit tumor cell proliferation, migration, and invasion." (PMID 36358967, 2022).